IL6 (interleukin 6)
Diseases named in the same sentence as IL6 in open-access papers (continued):
Sharing a sentence is not in itself a finding about the gene and the disease.
COVID-19 (continued). "Interleukin-6 (IL-6) inhibitors can be used for severe COVID-19 patients and are not recommended for mild COVID-19 patients." (PMID 35721224, 2022). "Expansion of CD14+CD16+ monocytes that express high level of IL-6 was significantly higher in COVID-19 patients admitted to ICU compared to those who did not." (PMID 36369012, 2022). "This suggests that antibodies targeting IL-6 and TNF-signalling may restore NK cell functions in COVID-19 patients." (PMID 35891232, 2022). "In agreement with others, higher IL-6 levels, a prognostic marker in COVID-19, coincided with a surge in Kyn abundance in non-HD patients." (PMID 36430566, 2022). "In addition, patients with COVID-19 had higher IFN-γ, IL-4, IL-5, and IL-6 concentrations compared to patients with influenza and higher IFN-γ and IL-10 concentrations compared to patients with bacterial CAP." (PMID 34987205, 2022). "When cytokine levels were evaluated in the culture media of PBMCs derived from healthy individuals and COVID-19 patients, a higher tendency to secrete cytokines such as IL-1b, TNF, IL-6, INFg, IL-17, MCP-1, and IL-10 was observed in cells exposed to SARS-COV2 infection." (PMID 35831294, 2022). "Thus, IL-6 derived from SARS-CoV-2 specific CD4+ T cells is required for cardiac complications and death in COVID-19 patients with DM." (PMID 36123740, 2022). "An overview of the literature indicates that IL-6, IL-2, IL-7, IL-10, granulocyte colony-stimulating factor (G-CSF), IFN- γ, inducible protein (IP)-10, TNF-α, MCP-1, macrophage inflammatory protein (MIP)-1α play a crucial role in the pathogenesis of COVID-19." (PMID 35619180, 2022). "SOTRs with COVID-19 have higher plasma levels of cytokines such as IFN-λ1, IFN-γ, IL-15, IL-18 IL-1RA, IL-6, MCP-2, and TNF-α as compared to healthy controls, and the levels of GM-CSF, IL-15, IL-6, IL-8, and IL-10 were associated with disease severity in SOTRs." (PMID 35075453, 2022). "In particular, IL-6 and CRP levels might be useful to distinguish between early-stage (mild to moderate) COVID-19 patients." (PMID 36219652, 2022). "The protein-protein interaction-level network obtained from the differentially expressed genes revealed elevated TNF-α signaling in the Activated CD4+ T cells, IL-6 signaling in the CD8+ TEM cells, which are indicative of elevated inflammatory response during active COVID-19." (PMID 36532041, 2022). "Given that plasma cytokine levels decrease after SARS-CoV-2 infection while IL-1β, IL-6, and TNF remain stable in individuals with ongoing PASC, we next asked whether there are patterns in active COVID-19 that provide a mechanistical link to this observation." (PMID 35732153, 2022). "Furthermore, CCL2, IL-6, and TNF-α expressions were higher in COVID-19 patients compared to controls (P<0.001)." (PMID 35982898, 2022). "The levels of lymphocyte subsets decreased and the level of IL-6 increased significantly in ICU COVID-19 patients compared with non-ICU COVID-19 patients." (PMID 35346253, 2022). "Elevated levels of IL-6, IL-10, and TNF-α in COVID-19 patients promote the expression of PD-1 and T-cell immunoglobulin mucin 3 (Tim-3) on the surface of peripheral T cells that act as exhaustion signals, resulting in decreased T-cell function and memory T-cell activity." (PMID 35615369, 2022). "The mean concentration of IL-6 in the non-severe COVID-19 group was 430.3 pg/ml, whereas that of the control group was 419.5 pg/ml." (PMID 35784318, 2022). "As expected, circulating levels of IL-6 and IL-10 were higher in ICU COVID-19 patients." (PMID 35637483, 2022). "Multi-organ failure may be attributed to excessive production of proinflammatory cytokines—the so-called “cytokine storm”, and interleukin 6 (IL-6) and tumor necrosis factor α (TNF-α) are the pivotal players in cytokine storm pathogenesis and COVID-19." (PMID 35277472, 2022).
COVID-19 (continued). "In COVID-19, the viral envelope E protein triggers the activation of the NF-κB inflammatory signaling cascade and the interaction with inflammatory factors, such as tumor necrosis factor-alpha (TNF-α) and interleukin 6 (IL-6)." (PMID 35990630, 2022). "Selected immunomodulators (e.g systemic corticosteroids, interleukin-1, interleukin-6 and JAK-inhibitors) were gradually added to the COVID-19 therapeutic repertoire and are used to mitigate excessive inflammatory responses associated with the disease progression." (PMID 35392095, 2022). "Patients with COVID-19 also display selective induction of the macrophages that produce IL-6, but not TNF-α and IL-1β, and this then directly promotes lymphocyte necrosis." (PMID 35464491, 2022). "IL-6 was highest in 50s’G, while it was lowest in 20s’G before the COVID-19 pandemic, whereas this trend was not significantly different among the groups during the pandemic." (PMID 35162870, 2022). "The mean IL-6 levels were recorded to be significantly higher in patients with severe COVID-19 compared with non-severe COVID-19 patients." (PMID 35215138, 2022). "We hypothesized that leukotriene inhibitors (LTIs), that have been shown to lower IL6 and IL8 levels, may have a protective effect in patients with COVID-19." (PMID 35836784, 2022). "Increased IL-6, MCP-1 and IL-10 have been detected in COVID-19 BALs compared to peripheral blood." (PMID 36211412, 2022). "Univariate and multivariate logistic regression analyses of IL-6 signalling components as predictors of COVID-19 severity (without death)." (PMID 35634332, 2022). "In line with the literature, IL-6 levels were also elevated in acute COVID-19 as compared with individuals without infection but not as prominently as in the bacterial pneumonia samples." (PMID 35732153, 2022). "High expression of neutrophil-related cytokines IL-8 and IL-6 in serum and neutrophilia has been described as a predictor of poor outcome, contributing to a cytokine storm and the further development of ARDS and organ failure in COVID-19 patients." (PMID 36139764, 2022). "However, galectin-9 plasma levels also correlated with pro-inflammatory mediator secretion (IL-6, TNFα, CXCL10) in dengue and COVID-19 infected patients." (PMID 36142892, 2022). "COVID-19 inflammatory markers were done for all the patients which included C-reactive protein (CRP), lactate dehydrogenase (LDH), D-dimer, ferritin, CK-MB and interleukin-6 (IL-6)." (PMID 35664398, 2022). "This post-COVID-19 inflammatory syndrome was originally diagnosed as Kawasaki disease; however, patients with MIS-C display more pronounced lymphopenia, thrombocytopenia, anemia, and elevated serum IFN-γ, IL-1β, IL-6, IL-10, and IL-17 levels." (PMID 35464491, 2022). "The clinical characteristics, treatment, laboratory parameters of IL-6, C-reactive protein (CRP), lymphocyte counts before and after TCZ therapy, and clinical outcomes in the 13 patients with COVID-19 were retrospectively evaluated according to the related medical records." (PMID 35308307, 2022). "Therefore, we analyzed the viral loads and the differential gene expression profiles of eight cytokines (IL-1, IL-2, IL-4, IL-6, IL-10 IFN-γ, TNF-α, and TGF-β1) in a total of 118 qPCR confirmed COVID-19 cases." (PMID 36584119, 2022). "Mean IL-6 concentrations were nearly 100 times higher in patients with cytokine release syndrome (3110.5 pg/mL), 27 times higher in patients with sepsis (983.6 pg/mL), and 12 times higher in patients with ARDS unrelated to COVID-19 (460 pg/mL)." (PMID 35053224, 2022). "Indeed, high serum levels of inflammatory cytokines such as interleukin-6 (IL-6), IL-8, and tumor necrosis factor-α (TNF-α) are observed in COVID-19 patients and predicted disease severity and poor outcome." (PMID 35075453, 2022).
COVID-19 (continued). "Cytokines, such as IL-1β, IL-6, IFN-γ-induced protein 10 (IP-10), TNF-α, IFN-γ, macrophage inflammatory protein-1α and-1β (MIP-1α and-1β), and vascular endothelial growth factor (VEGF) are raised in COVID-19 patients." (PMID 36439786, 2022). "Although IL-6 levels were high in patients with dengue who proceeded to develop DHF, IL-6 levels were several fold lower in the critical phase in patients with dengue compared to COVID-19." (PMID 35786403, 2022). "The cytokine storm has already been attenuated following recovery from COVID-19, as levels of TNF-α, free active TGF-β, IFN-γ, IL-1β, IL-2, IL-4, IL-6, IL-8, IL-10, IL-12p70, IL-17 and MCP-1/CCL2 during convalescence were not higher compared to healthy volunteers." (PMID 35757700, 2022). "Regarding the hyperinflammation, we observed BK1-8 was positively and significantly related to four out of five inflammation markers studied (CRP, ferritin, IL-1β, IL-6, and TNF-α), suggesting a potential role of this peptide in patients with COVID-19’ inflammation." (PMID 35812405, 2022). "The importance of OSM during COVID-19 development can be inferred from the cluster analysis of selected markers, which showed both IL-6 and OSM as the markers that differentiated ICU and non-ICU patients." (PMID 35163735, 2022). "Systemic inflammation with increased synthesis of IL-6, as well as interferon-γ, IL-1β, IL-33 and TNF, is the basis of the progressive course of COVID-19 and seriously affects erythropoiesis through various mechanisms supported in part by abnormal iron metabolism." (PMID 35327355, 2022). "Moreover, a selected set of serum soluble mediators (IL-6, IFN-γ, IL-1Ra, IL-13, PDGF and IL-7) were pointed out as promising biomarkers for the clinical management of severe COVID-19 patients." (PMID 36451835, 2022). "Compared with the HC group, increased serum levels of MMP-9 and IL-6 were found in COVID-19 patients regardless of the disease severity." (PMID 36139764, 2022). "The elevated expression of IL-6 and TNF- ɑ in COVID-19 is indicative of a cytokine storm." (PMID 35573503, 2022). "IL-6 and IL-15 were not increased in the mild COVID-19 group but were significantly elevated in the moderate and severe groups." (PMID 35663992, 2022). "The significant upregulation of IL-6 and RIG-I in symptomatic COVID-19 patients could be mediated by hsa_circ_0000479 through sponging the hsa-miR-149-5p." (PMID 36081604, 2022). "Furthermore, plasma IL-8, IL-6, TNFRSF11B, and CSF EZR levels were allied to severe COVID-19 using the ordinal backward and best linear model, whereas plasma 4E-BP1 and CSF levels of PD-L1, BMP-4, CLEC10A and ROBO2 withstanded using one model only." (PMID 36351919, 2022). "We found for CD4+ T cells, COVID-19 plasma exosomes obtained from patients upon admission stimulated production of IL-6, IL-8, and TNF-α compared to plasma exosomes from non-COVID donors, with expression of IFNγ not being significantly affected." (PMID 36526691, 2022). "Moreover, IL-6 up-regulates levels of ACE2, the natural receptor of COVID-19, finally amplifying the virus effects on endothelial cells." (PMID 35050236, 2022). "The Infectious Diseases Society of America (IDSA) guidelines, as of August 31, 2021, suggested the use of TCZ in hospitalized patients with progressive severe or critical COVID-19 who have elevated markers of inflammation such as C-reactive protein, serum ferritin, LDH, and IL-6." (PMID 35657993, 2022). "On the other hand, the suppressor of cytokine signaling 3 (SOCS3) pathway, which has negative feedback on IL-6 production, is downregulated during COVID-19, thus contributing to IL-6 hyper-production." (PMID 35572540, 2022). "In contrast, COVID-19 plasma exosomes were unable to induce expression of IL-6 by CD8+ T cells relative to treatment with non-COVID-19 plasma exosomes." (PMID 36526691, 2022).
COVID-19 (continued). "Similarly, IL-6 and CRP ranged among the strongest predictors for ICU admission or death at 30 days in COVID-19 (AUC for IL-6 0.794 [95%CI 0.694–0.894]; AUC for CRP 0.807 [95%CI 0.721–0.893]) and both controls." (PMID 35622838, 2022). "Moreover, monocytes fall into clearly distinct clusters, annotated by their highly expressed markers, IL-6+ monocytes, GPBAR1+ monocytes and CXCL10+ monocytes, and were mostly derived from neonates with COVID-19." (PMID 34937051, 2022). "COVID-19 is characterized by an overwhelming state of inflammation with an elevated level of circulating chemokines (e.g., MCP-1 and RANTES) and cytokines, such as IL-6, IL-8, and TNF-α eventually leading to a multi-organ dysfunction that has been called COVID-19 cytokine storm syndrome (CSS)." (PMID 35211011, 2022). "Here both M.tb and M.tb-EST12 significantly induced pro-inflammatory cytokines IL-6 and TNF-α expression, suggesting that M.tb-induced pro-inflammatory cytokines might possibly have implication on inflammation of severity COVID-19." (PMID 36003390, 2022). "There is also a clear association between others such as IP-10, MCP-1, MIP-1α, TNF-α and IL-6 and COVID-19 severity when comparing ICU-patients with non-ICU patients." (PMID 36466830, 2022). "In conclusion, from a technical and analytical perspective, the results of this study show that the QDTI assay proves to be non-inferior to the Luminex assay in terms of accurate IL-6 measurement for patients hospitalized with COVID-19." (PMID 35626318, 2022). "Severe COVID-19 sufferers demonstrated increased levels of non-classical monocytes, several plasma chemokines such as CXCL9 cytokines (IL-6 and IL-10), and ROS as opposed to mild COVID-19." (PMID 36016187, 2022). "In SARS-CoV-2 infected lung, presence of IL-1β, TNFα, IL-6, and IL-8 indicate IL-17 induced MAPK and NF-κB mediate signaling; MAPK was shown to be activated during the acute phase of SARS-CoV-2 infection in nasopharyngeal swabs of severe COVID-19 patients." (PMID 36136963, 2022). "One of the most striking clinical features of COVID-19 patients is the dysregulated immune response, which leads to a cytokine storm, that is, the overproduction of proinflammatory cytokines (TNF-α, IL-1, and IL-6) and chemokines (IL-8)." (PMID 36211421, 2022). "A recently published study showed that nonsurvivor COVID-19 patients had increased levels of LPS, IL-6, and TNF-α, among others." (PMID 35563697, 2022). "Of note, we observed that COVID-19 patients with high pGSN/IL-6 and pGSN/IgM presented with mild disease did not require ICU admission and were more likely to be discharged." (PMID 36148234, 2022). "Meanwhile, the high concentrations of IL-6 and IP-10 in patients’ sera, together with the infiltrating macrophages, have been depicted as the “immune signature” of SARS-CoV-2 and as the prototype factors driving COVID-19 progression." (PMID 35632693, 2022). "We included in our tests a set of cytokines and chemokines with serum concentrations that were shown to increase during COVID-19, and this increase might also be reflected in breastmilk: TNF-α, IL-6, IFN-β, IL-1β, IFN-γ, IL-2, GM-CSF and IL-5, IP-10." (PMID 36560410, 2022). "Comparison of plasma FABP2 levels with other circulating metabolites and patient clinical data in the more severe COVID-19 group showed the strongest negative associations (i.e. high level when FABP2 is low) with CRP, Il–6 and zonulin." (PMID 36335131, 2022). "Elevated serum IL-6 levels predict mortality in approximately 50% of HF patients, and high tumor necrosis factor (TNF)-α levels in patients with severe COVID-19 may exacerbate the development of HF." (PMID 36420258, 2022). "A previous study suggested a reduction in T cell counts in COVID-19 patients and high levels of pro-inflammatory markers such as TNF-α, IL-6, IL-8, and IL-10 may be a potential reason for the killing of T cells." (PMID 35890093, 2022).
COVID-19 (continued). "Another therapeutic approach for managing COVID-19 is targeting the Janus kinase/signal transducer and activator of transcription (JAK/STAT) pathway, which mediates the signaling of multiple pro-inflammatory cytokines, including IL-6." (PMID 35707401, 2022). "Advanced disease is characterized by a hyper-inflammatory state, with high levels of circulating pro-inflammatory cytokines, such as Interleukin-6 (IL-6), Tumor Necrosis Factor-alpha (TNF-α) and interferon-gamma (IFN-γ), which have been blamed for the extensive COVID-19-related tissue damage." (PMID 36680091, 2022). "Biomarkers, such as neutrophile-to-lymphocyte ratio and interleukin-6, were established as independent predictors of COVID-19 worsening, although their evaluation was not possible until the blood sample was taken." (PMID 35683347, 2022). "On the other hand, the plasma concentration of IL-6 only correlated with that of cell-free nucleosomes, but not with dsDNA in the COVID-19 group." (PMID 36466824, 2022). "In the present study, we compared the inflammation markers NP, CRP, and IL-6 in the plasma of COVID-19 and non-COVID-19 patients." (PMID 35529699, 2022). "Inflammation, and thus increases in cytokines (such as IL1, IL6, IL8) typical of periodontitis, is the link with COVID-19; it may also aggravate the conditions of COVID-19 infection." (PMID 35224542, 2022). "Conforming with previous reports, the level of the following markers, CA12, soluble CD40, IL-6, IL-8, soluble PD-L1, and VEGF, were significantly increased by 1.5-fold, 1.5-fold, 6-fold, 2-fold, 2-fold, and 1.5 fold, respectively, in COVID-19 deceased patients compared to control cohort (p ≤ 0.05)." (PMID 36428847, 2022). "Using data from two Mount Sinai Health System hospitals, we identified a cohort of 206 COVID-19 patients without indications of prior heart disease for whom imaging data along with troponin I and IL-6 levels were available." (PMID 34669512, 2022). "Interleukin-6 (IL-6) blockers including tocilizumab and sarilumab were approved by the U.S. Food and Drug Administration (FDA) in June 2021 for the treatment of patients with moderate to severe COVID-19." (PMID 36503381, 2022). "A prior cohort analysis found that IL-6 expression was substantially higher in COVID-19 patients, but that it varied greatly across ICU and non-ICU patients." (PMID 36506506, 2022). "However, they were lower in viral controls (IL-6 4.61 pg/ml [IQR 2.09–16.51], CRP mg/l 3.3 [IQR 0.9–15.0], PCT 0.030 ng/ml [IQR 0.014–0.056]), than in COVID-19 with p-values again <0.001 for all comparisons." (PMID 35622838, 2022). "Our results showed that serum IL-2, IL-4, IL-6, and IL-10 levels were elevated in COVID-19 patients compared to healthy controls, and IL-6, IL-8, and IL-10 levels were increased in severe COVID-19 cases compared to nonsevere patients." (PMID 35540724, 2022). "In addition, we evaluated the potential bindings of emetine with the LUAD/COVID-19 targets (SLC6A4, MIF, DPP4, PRF1, SERPING1, and IL6)." (PMID 35733175, 2022). "In a situation representative of severe COVID-19 (3 ng/ml IL-6 in BAF; mAb penetration into BAF 10% of that in plasma), a single injection of siltuximab inhibited IL-6 bioactivity by 90%, with an immediate resumption of IL-6 bioactivity within 24 hours." (PMID 35928820, 2022). "COVID-19 patients show normal level of monocytes with activated phenotype, as evidenced by high FSC (forward side scatter) and potential to secrete cytokines, such as IL-6, IL-10, and TNF." (PMID 35883618, 2022). "The other inflammatory markers were elevated in patients during the acute phase of COVID-19, including CRP levels (56mg/L vs. 12mg/L, p-value < 0.001), IL-6 (49pg/mL vs. 17pg/mL, p-value < 0.001), fibrinogen (5.1g/L vs. 3.7g/L, p-value < 0.001), and D-dimers (331ng/mL vs. 262ng/mL, p-value < 0.001)." (PMID 35160114, 2022).